CRP (C-reactive protein)
Diseases named in the same sentence as CRP in open-access papers (continued):
Sharing a sentence is not in itself a finding about the gene and the disease.
sarcopenia (continued). "Third, the levels of inflammatory cytokines other than CRP were not measured in this study; thus, we could not thoroughly evaluate the association between inflammation status and sarcopenia." (PMID 29447254, 2018). "The clinical status of the systemic inflammatory response (based on CRP level) has been identified as an independent prognostic factor in various types of cancer, and several lines of evidence have suggested that systemic inflammation has an important role in aggravating sarcopenia." (PMID 28684736, 2017). "Based on the prognostic significance of sarcopenia beyond CRP demonstrated in this study and the noncancer‐specific nature of CRP, sarcopenia appears to surpass CRP as a prognostic factor associated with host inflammatory responses to tumors in UTUC patients treated with RNU." (PMID 27350148, 2016). "A positive association was found between UA and CRP (inflammation), regardless of body composition (hyperadiposity and/or sarcopenia), gender, age and the presence of MS and its components, which means that there are a direct relation between these two factors." (PMID 23311699, 2013). "This study aimed to evaluate the correlation between inflammatory biomarkers such as C-reactive protein (CRP), tumor necrosis factor-alpha (TNF-α), interleukin-6 (IL-6), and the anabolic hormone insulin-like growth factor-1 (IGF-1) with sarcopenia." (PMID 42267078, 2026). "Body composition and anthropometric parameters, high‐sensitive C‐reactive protein (hs‐CRP), the model for end‐stage liver disease‐Na (MELD‐Na), frailty, sarcopenia, and muscle strength were assessed at the initiation and upon completion of the trial." (PMID 41473401, 2026). "Elevated levels of IL-6, CRP, and TNF-α have been investigated as possible pathophysiological mechanisms involved in sarcopenia." (PMID 41465572, 2025). "Receiver operating characteristic (ROC) curve was used to evaluate the performance of the Hs-CRP/HDL-C ratio, Hs-CRP, and HDL-C indicators in predicting sarcopenia." (PMID 40672942, 2025). "The p for trend was statistically significant (p<0.05) in all models, indicating a dose-response relationship between the Hs-CRP/HDL-C ratio and the likelihood of sarcopenia." (PMID 40672942, 2025). "Furthermore, patients with sarcopenia exhibited a greater prevalence of nutritional risk (NRS ≥ 3) and COPD, alongside lower serum albumin levels, higher total bilirubin, elevated serum creatinine, reduced triglycerides, increased C-reactive protein, and lower eGFR (all p values < 0.05)." (PMID 41262732, 2025). "Elevated levels of inflammatory cytokines, such as tumor necrosis factor-alpha (TNF-α), interleukin-6 (IL-6), and C-reactive protein (CRP), have been consistently observed in older adults with sarcopenia." (PMID 40283772, 2025). "In contrast, more objective physiological measures like sarcopenia, EPR, and CRP retained their predictive value." (PMID 38646255, 2024). "We further explored the mediating roles of CRP and BMR in the improvement of cognition and sarcopenia‐related traits by glucosamine using MVMR coupled with a two-step MR method, respectively." (PMID 39764251, 2024). "In fact, elevated circulating levels of typical inflammaging mediators, such as Interleukin 6 (IL6), Tumor necrosis factor α (TNFα) and C-reactive protein (CRP), have been found in patients with sarcopenia." (PMID 38808117, 2024). "According to the adjusted analysis, sarcopenia (adjusted OR (aOR) -1.97 (1.87-4.44)), EPR (aOR-2.33 (1.02-5.32)), and CRP (aOR-2.09 (1.01-3.18)) remained significant." (PMID 38646255, 2024). "Other possible biomarkers with sarcopenia includes men’s hemoglobin levels and women’s levels of HDL, C-reactive protein leukocytes, and lymphocytes." (PMID 39186818, 2024).
sarcopenia (continued). "Additionally, response to induction systemic therapy, serum CRP level, and older age at diagnosis (≥75 years) could be used as a prognostic factor instead of cachexia or sarcopenia, and in turn they could play a fundamental role in selecting patients with sOMD fit for radical treatment." (PMID 38201657, 2024). "According to the multivariate logistic regression analysis, sarcopenia (adjusted Or (aOR)-1.97 (1.87-4.44)), EPR (aOR-2.33 (1.02-5.32)), and CRP (aOR-2.09 (1.01-3.18)) remained significant." (PMID 38646255, 2024). "Data on demographics, lung function, symptoms, nutrition, frailty, sarcopenia, the eosinophil-to-platelet ratio (EPR), and CRP were extracted." (PMID 38646255, 2024). "This study focused on randomized controlled trials (RCTs) that examined the effects of RT on interleukin-6 (IL-6), tumor necrosis factor-α (TNF-α), C-reactive protein (CRP), and interleukin-10 (IL-10) about sarcopenia." (PMID 38863698, 2024). "Thereby, an increase in the levels of inflammatory markers, such as CRP and NLR, has been significantly correlated with cancer cachexia and sarcopenia." (PMID 36831431, 2023). "Elevated C-reactive protein (CRP), IL-6, and TNF-alpha have shown the strongest correlation with sarcopenia and frailty, resulting in extreme muscle wasting due to the promotion of catabolic signals mediated through these proinflammatory cytokines." (PMID 36979712, 2023). "Our data support a chronic low-grade pro-inflammatory systemic status in sarcopenia, as suggested by higher circulating levels of ESR, CRP, fibrinogen, ferritin, and α2-globulins, which are markers of inflammation." (PMID 38001845, 2023). "For the first time, we demonstrated a significantly higher CRP/albumin ratio and an elevated level of cfDNA in the group with diagnosed sarcopenia compared to the older adult without sarcopenia, thereby indicating that the two parameters could be used as novel biomarkers of sarcopenia." (PMID 37465171, 2023). "There are higher circulating levels of inflammatory cytokines such as interleukin-1 (IL-1), interleukin-6 (IL-6), C-reactive protein (CRP), and tumour necrosis factor-α (TNF-α), which lead to both tissue depletion and sarcopenia." (PMID 37077743, 2023). "In the entire patient cohort, univariate Cox regression analysis revealed that BMI, sarcopenia, KPS score, levels of hemoglobin, hypersensitive C-reactive protein (hCRP) and albumin were significant prognostic factors for OS (all p < 0.05)." (PMID 36969820, 2023). "Previous epidemiological studies have shown that patients with sarcopenic obesity have higher levels of cytokines, such as C-reactive protein (CRP), interleukin-6 (IL-6), and monocyte chemotactic protein-1 than those with sarcopenia." (PMID 36895276, 2023). "Of these inflammatory factors, C-reactive protein (CPR), interleukin-6 (IL-6) and tumor necrosis factor-a (TNF-a) are critical for predicting the incidence of sarcopenia." (PMID 36895911, 2023). "In RCC studies, sarcopenia with elevated inflammation, e.g., the modified Glasgow Prognostic Score (mGPS), neutrophil-to-lymphocyte ratio (NLR) and C-reactive protein (CRP), was investigated for predicting inferior overall survival (OS)." (PMID 36591466, 2022). "Systemic chronic inflammation and increased inflammatory markers such as CRP, IL-6, and TNF-α are related to increased muscle mass degradation and appearance of sarcopenia in ND-CKD patients." (PMID 35463026, 2022). "Evidence has been reported that the circulation level of TNF-α, C-reactive protein (CRP), and IL-6 correlated with a functional decline of skeletal muscle and muscle mass, suggesting a direct role of these molecules in sarcopenia." (PMID 35891702, 2022). "Another highlight in the present study was that in the sarcopenia group, both TSF and R-Leg-M predicted significant variations in CRP levels, while MAMA explained significant variations in TNF-α levels." (PMID 36291982, 2022).
sarcopenia (continued). "In the present study, IL-6 was positively correlated with TUG, while CRP was positively correlated with TSF and inversely correlated with R-leg-M in the sarcopenia group only." (PMID 36291982, 2022). "In addition, sarcopenia leads to mitochondrial DNA (mtDNA) mutations, increased release of reactive oxygen species (ROS), increased pro-inflammatory agents such as interleukin-6 (IL-6), and tumor necrosis factor-α (TNF-α), interleukin-1 (IL-1), as well as C-reactive protein (CRP)." (PMID 35250869, 2022). "Of the various harmful influences of inflammation, the elevated concentration of c-reactive protein (CRP), IL-6, and TNF-alpha, have been strongest correlates of sarcopenia and frailty." (PMID 34328636, 2021). "The prevalence of sarcopenia (48.68 vs. 31.43%, P = 0.043), PG-SGA≥4 (39.47 vs. 17.14%, P = 0.003), and high-level CRP (27.63 vs. 11.43%, P = 0.021) were higher in the moderate to severe disability group than in the without to minimal disability group." (PMID 34307398, 2021). "In details, patients with sarcopenia showed higher white cell counts and neutrophils, as well as higher NLR, LLR, CRP and fibrinogen." (PMID 34944975, 2021). "Inflammatory markers including interleukin 6 (IL-6), C Reactive Protein (CRP) and tumor necrosis factor-alpha (TNF-a) were shown to positively correlate with sarcopenia." (PMID 33902634, 2021). "Additionally, vitamin D supplementation may decrease serum levels of the parathyroid hormone and inflammatory cytokines (i.e., TNF-α and CRP) in HF patients, therefore its supplementation is regarded as an appealing strategy to manage sarcopenia in the setting of HF." (PMID 31947528, 2020). "The patients with sarcopenia in this study showed a high level of inflammation related markers such as CRP and NLR, suggesting that sarcopenia and inflammation are markers of aggressive tumors." (PMID 32984018, 2020). "The 12 variables were as follows; sex, pathology, ECOG, carbohydrate antigen 19-9 (CA 19-9), CRP, albumin, protein, cholesterol, BUN, NLR, Sarcopenia, group stratification based on sarcopenia and NLR." (PMID 32984018, 2020). "We showed levels of homocysteine, CRP and NLR were higher in patients with severe sarcopenia, suggesting a major role of inflammation in sarcopenia severity in cirrhosis." (PMID 33187310, 2020). "Serum levels of TNF-α, IL6 and C-reactive protein (CRP) are all increased in ageing and have been proposed to be important mediators of sarcopenia as changes are correlated with a decrease in muscle mass, performance, function, strength and fitness." (PMID 30259289, 2018). "The highest PLR level group had a higher prevalence of sarcopenia, a lower SMI and a slower gait speed; moreover, this group was older, had a higher C-reactive protein (CRP) and lower albumin levels." (PMID 29192175, 2017). "Frailty exacerbates this process, as inflammatory markers such as IL-6 and C-reactive protein (CRP) further stimulate the RAAS, creating a cycle where RAAS-mediated inflammation worsens sarcopenia and frailty-related metabolic dysfunction amplifies cardiovascular damage." (PMID 41282339, 2025). "The role of IL-6 in cachexia-related sarcopenia has been previously discussed in this section and elevated levels of TNF-α, IL-6 as well C-reactive protein (CRP) have been detected in sarcopenic people, further suggesting a link between systemic inflammation and muscle degeneration." (PMID 40181329, 2025). "This study investigated the correlation of known sarcopenia biomarkers—adiponectin, myostatin, P3NP, CRP and TNF‐α—measured from plasma‐derived EVs with muscle mass, function and performance in an Osteoporosis Sarcopenia cohort at the Seoul National University Bundang Hospital." (PMID 40162588, 2025). "Hemoglobin and albumin were lower, and CRP and ESR were higher in the sarcopenia group." (PMID 40476129, 2025).
sarcopenia (continued). "CRP, a non-specific marker of systemic inflammation, has been shown in previous research to be elevated in patients with sarcopenia compared to non-sarcopenic individuals." (PMID 39979762, 2025). "Using the OsteoSarcopenia cohort, we performed a proteomic analysis of human plasma‐derived EVs to examine the relationships between sarcopenia biomarkers (myostatin, adiponectin, P3NP, CRP and TNF‐α) and sarcopenia‐related factors (muscle mass, muscle function and muscle performance)." (PMID 40162588, 2025). "Concerning CRP and ESR, this study showed that there was a statistically significant difference in CRP levels between the two groups with and without sarcopenia at one-month and six-month follow-up; levels were higher in patients in the sarcopenia group." (PMID 40476129, 2025). "Nevertheless, in the present study, inflammation did not contribute to sarcopenia, as shown by CRP and ESR concentrations." (PMID 40019564, 2025). "Our results indicated that CRP levels showed a nonlinear correlation with sarcopenia among adults in the US." (PMID 39969369, 2024). "Compared with the non-sarcopenia participants, sarcopenia patients were older and thinner (P < 0.05), and had lower levels of ALT, TBil, and TG (P < 0.01) but higher levels of FBG, BUN, HDL-C, and hs-CRP (P < 0.01)." (PMID 39361190, 2024). "Further, in a study of 90 individuals with IBD, those with sarcopenia had higher levels of C-reactive protein (CRP), a circulating inflammatory marker, as compared to those without sarcopenia." (PMID 38911683, 2024). "In comparison to sCr, CysC is independent of sex, age, and sarcopenia, but it is influenced by high levels of C reactive protein, thyroid dysfunction, and smoking." (PMID 38732353, 2024). "Consistent with this, we observed significantly higher values of inflammation markers, particularly tripled values of CRP and almost doubled values of IL-6, in sarcopenic obese subjects compared to the group of obese patients without sarcopenia." (PMID 38921440, 2024). "However, findings from previous studies on the relationship between C-reactive protein (CRP) levels and sarcopenia are limited." (PMID 39969369, 2024). "Whether newer biomarkers such as sarcopenia and the EPR provide additional predictive value over CRP alone is unknown." (PMID 38646255, 2024). "The putative effects of sarcopenia on MACE were possibly not mediated by a causal pathway involving CACS, CRP, serum albumin, or vitamin D levels." (PMID 39315011, 2024). "Values of CRP and bilirubin were higher in the group with both sarcopenia and frailty vs. those without both sarcopenia and frailty." (PMID 39795544, 2024). "In summary, sarcopenia, the EPR, and CRP levels are promising systemic biomarkers that may predict clinically important COPD outcomes, including exacerbations." (PMID 38646255, 2024). "Regular glucosamine use enhances cognitive function and postpones sarcopenia for preserving the functional capacities necessary, and the impact of glucosamine on cognition and sarcopenia could be partially attributed to the mediation of BMR and CRP." (PMID 39764251, 2024). "Notably, CRP and CEA levels gradually increased in the order of normal status, followed by pre–respiratory sarcopenia, and then respiratory sarcopenia (linear P for trend < .001) (eFigures 4A and 4B in Supplement 1)." (PMID 39475952, 2024). "We found that both MAFLD prevalence and severity was significantly associated with sarcopenia, further mediation analysis identified that CRP and HDL may mediate the impact of sarcopenia on MAFLD (p < 0.05)." (PMID 38491346, 2024). "Fecal calprotectin (p = 0.001), ESR (p = 0.003), and CRP levels (p < 0.001) were significantly higher in patients with sarcopenia than in patients without sarcopenia." (PMID 38438954, 2024).
sarcopenia (continued). "Our results remained significant after adjusting for the effect of age, sex, co‐morbidity, and levels of CRP, indicating that GDF‐15 may be a potential biomarker of sarcopenia in multimorbid acutely admitted older patients." (PMID 38890783, 2024). "Chronic inflammation also affects sarcopenia, as pro-inflammatory cytokines such as interleukin-6 (IL-6), TNF-α, and C-reactive protein (CRP) increase adiposity and impair the protein synthesis pathway in skeletal muscles, which promotes the pathogenesis of sarcopenia." (PMID 36474318, 2023). "In addition, patients with sarcopenia have a significantly higher erythrocyte sedimentation rate (ESR) and CRP levels than controls, and ROS/RNS plays an important role in the development of sarcopenia." (PMID 37932727, 2023). "In our study, we noted lower values of inflammatory markers (CRP, CRP/albumin ratio, TNFα, IL-6, IL-1β, cfDNA) in the no-sarcopenia group, as opposed to the sarcopenia group." (PMID 37465171, 2023). "A significantly higher level of CRP was recorded in the group with sarcopenia compared to without sarcopenia, which clearly indicates the relationship of systemic inflammation and skeletal muscle degradation." (PMID 37465171, 2023). "So far, the prognostic significance of CRP/albumin ratio in the aging and inflammatory processes in sarcopenia has not been reported." (PMID 37465171, 2023). "Albumin, CRP, vitamin D, and serum folate should not be overlooked when screening for sarcopenia in geriatric settings, particularly in the male population." (PMID 37110223, 2023). "Albumin, CRP, vitamin D, and serum folate should not be neglected in screening for sarcopenia in the aging population." (PMID 37110223, 2023). "Moreover, among the elderly higher levels of p-selectin, C-reactive protein (CRP), and interferon γ-induced protein 10 correlated with sarcopenia and worse performance status." (PMID 36428939, 2022). "Compared with RA without sarcopenia, ESR and CRP in female RA with sarcopenia were higher, and the differences were statistically significant (P < 0.05–0.001), suggesting higher disease activity." (PMID 35676311, 2022). "In this cross-sectional study, we aim to compare inflammatory factors levels, including IL6, CRP, and TNFα, between sarcopenia and non-sarcopenia in Iranian adults." (PMID 35361818, 2022). "Consistent with previous studies, This study showed that the level of C-reactive protein was increased in HD patients who developed sarcopenia compared to non-sarcopenia patients." (PMID 36138351, 2022). "For instance, subjects with sarcopenia also had higher levels of hs-CRP compared with participants without sarcopenia." (PMID 35162699, 2022). "The results of a meta-analysis and systematic review showed that serum IL-6 and TNF-α levels in patients with sarcopenia were not significantly different from those in the control group, while the level of C-reactive protein (CRP) in serum increased." (PMID 35406642, 2022). "In the Copenhagen sarcopenia study, elderly women also had significantly higher levels of CRP, TNF-α, and IL-6, compared with middle-aged women and significantly higher levels of CRP, TNF-α, IL-1β, and IL-4 compared with young girls." (PMID 36291982, 2022). "Significant differences in CRP and functional capacity between the sarcopenia and non-sarcopenia groups were found (p <.05)." (PMID 35570546, 2022). "Inversely, the participants with possible sarcopenia had higher level of CRP, than those without sarcopenia (p<0.001)." (PMID 33661964, 2021). "The dose–response curves suggested that the odds of sarcopenia increased with CRP (p-nonlinearity = 0.21) and SII (p-nonlinearity = 0.02) in a monotonic pattern, although the curve for CRP was non-significant when the level was lower than ~5 mg/L." (PMID 34836213, 2021).